ICAM1 (intercellular adhesion molecule 1)
Diseases named in the same sentence as ICAM1 in open-access papers (continued):
Sharing a sentence is not in itself a finding about the gene and the disease.
tumor (continued). "The expression of angiogenic and pro-tumor molecules including VEGF and ICAM-1 was also decreased in the CPSI-1306-treated groups indicating the anti-angiogenic potency of CPSI-1306 against TNBC." (PMID 32943608, 2020). "Consistently, IHC staining of xenograft tumor tissues using TGF-β, BMP4, ICAM1 and VCAM1 antibodies indicated suppression of the TGF-β signaling pathway status in PGAM1 silencing cancer cells compared to that in the control group." (PMID 32855383, 2020). "This suggests the role of ICAM-1 and LFA-1 interaction in providing an inflammatory microenvironment suitable for colonization of tumor cells in the liver." (PMID 32848838, 2020). "The up-regulation of adhesion molecules such as ICAM1 and VCAM1 by tumor vasculature plays a critical role in the recruitment of leukocytes to the tumor tissue and activation of endothelial cell." (PMID 32340193, 2020). "Primary specimen tumor samples were also analyzed for VEGF-A, VEGFR-1, VEGFR-2, bFGF, E-selectin, PIGF, neuropilin (NRP), ICAM-1 and CD31." (PMID 32759686, 2020). "Immune cell effectors must receive cues to adhere and extravasate from the vasculature in order to enter the tumor microenvironment and we observed that 2′3′-cGAMP and IFN-β co-operate to upregulate E-selectin, ICAM-1, and VCAM-1." (PMID 33013881, 2020). "Also, Tregs from NI ad I TDLN share CD58, ITGAM, MCAM, CEACAM4, SELPLG, and HMMR expression, which could ensure recirculation among TDNLs; and Tregs from I TDLN and tumor Tregs share ICAM1 expression, which could be responsible for the migration among tissues with presence of tumor cells." (PMID 32601304, 2020). "Agonistic antibodies targeting CD137 increase E-selectin, ICAM-1, and VCAM-1 surface expression on tumor vessels." (PMID 33262763, 2020). "Lastly, after the purified tumour-infiltrating PMN-MDSCs were cultured for 24 h in vitro, cells from the HSD group expressed more TNF-α and ICAM-1 and less prostaglandin E2 (PGE2), Arg1, CCL2 and CCL5 than those from the NSD group." (PMID 32265505, 2020). "In conclusion, we confirmed that ICAM1-specific CAR-T cells were able to efficiently recognize ICAM1 expressing TNBC cells, and they reduced the TNBC tumor growth effectively both in vitro and in vivo." (PMID 33072116, 2020). "CD54, also known as ICAM -1, is a transmembrane glycoprotein of the immunoglobulin superfamily, involved in tumor cell immune regulation, angiogenesis, invasion and distant metastasis." (PMID 33505909, 2020). "To assess ICAM1 as a potential ADC target, we first determined the in vivo tumor‐specificity of ICAM1 antibody in an orthotopic PC tumor model." (PMID 33344137, 2020). "Our previous study also showed that ICAM-1 and VCAM-1 are involved in tumor growth and migration and the adhesion of cancer cells to other organs." (PMID 32466580, 2020). "In vitro studies (Caco-2 and HT-29 cells) of the mechanisms of tumor cell metastasis showed that GRP promotes tumor cell motility and attachment to ECM, as a result of upregulation of Intercellular Adhesion Molecule-1 (ICAM-1) via FAK." (PMID 32429087, 2020). "The traditional, tumor-cytotoxic N1 phenotype has the potential to kill tumor cells, due to elevated levels of immune-activating factors (e.g., TNF-α, ICAM-1, FAS) and direct antibody-dependent cytotoxicity." (PMID 33171818, 2020). "An increase in the expression level of Intercellular Adhesion Molecule 1 (ICAM-1), which is a ligand for LFA-1, was also demonstrated, observing that this adhesion molecule was upregulated in tumor vessels after applying irradiation." (PMID 33218092, 2020). "The concentration of TNF-α and immunoglobulin-like cell adhesion molecules like ICAM-1 and VCAM-1 will trigger the chemotaxis which is directly related to the metastasis of tumor cells by vascular penetration." (PMID 32764400, 2020). "We fluorescently labeled ICAM1 monoclonal antibodies with AF‐647, a red fluorescent dye, (ICAM1‐AF) and intravenously injected them into PANC‐1 tumor‐bearing mice." (PMID 33344137, 2020).
tumor (continued). "We have developed a proof‐of‐principle ICAM1 ADC that induces potent and durable PC tumor regression in vivo." (PMID 33344137, 2020). "Our results obtained from 1-week tumor-bearing mice suggested that due to the higher expression of CD45, CD11b, CD11c, CD49d and ICAM-1 on PB CD62Ldim neutrophils, the adhesion of CD62Ldim neutrophils was stronger than that of CD62Lhi neutrophils." (PMID 33178575, 2020). "We chose ICAM1 and VCAM1, two cell-cell adhesion molecules required for the transmigration step of tumor metastasis." (PMID 32090682, 2020). "The highly angiogenic nature of HCC is associated with increased classical growth factors such as VEGF and PDGF, whilst classical adhesion molecules such as ICAM-1 and VCAM-1 are preferentially expressed on tumour tissue." (PMID 32982772, 2020). "In agreement with other tumor types, VEGF-A, and ICAM-1 levels found to be promising predictive biomarkers." (PMID 32759686, 2020). "We tested the ability of AIC100 to cross-react with mouse ICAM-1 in order to demonstrate that the toxicity of AIC100 from on-target, off-tumor killing can be examined in our preclinical model." (PMID 31337787, 2019). "Because LFA-1 is the principal canonical ligand for ICAM-1, in the second set of experimental conditions we blocked CD11a subunit of LFA-1 in the tumor cells with specific antibodies before co-culturing them with LSECs." (PMID 31511625, 2019). "Increased expression of adhesion molecules—intercellular adhesion molecule 1 (ICAM1) and VCAM1—in tumor vessels enables tumor infiltration by T lymphocytes." (PMID 31261963, 2019). "Because EWS-FLI1 low cells express more basal ICAM-1 and tumor ICAM-1 can enhance tumor cell: T-cell interaction and T-cell activation, we hypothesized that EWS-FLI1 low cells would be more susceptible to T-cell mediated tumor cell killing as compared to tumor cells with higher EWS-FLI1 expression." (PMID 31164960, 2019). "Instead, IL-33 EO expressed increased levels of ICAM-1 and CD11b/CD18, and both molecules (mostly CD11b/CD18) polarized to the EO-tumor cell synapses." (PMID 31717819, 2019). "N1 neutrophils reduce tumor immunosuppression through the production of several molecules, such as TNF-α, ROS (Reactive oxygen species), ICAM-1 (Intercellular Adhesion Molecule 1), and Fas." (PMID 31013961, 2019). "After irradiation costimulatory molecules (CD80), adhesion molecules (like intercellular adhesion molecule 1 (ICAM-1)), or stress ligand (NKG2DL) levels are increased on the surface of tumor cells." (PMID 31261963, 2019). "TNF-α can also stimulate the transcription of genes encoding endothelial cell adhesion molecules, including E selectin, ICAM-1, VCAM-1, and Madcam1, which are closely related to tumor metastasis and angiogenesis." (PMID 31600735, 2019). "In order to find the activating receptors responsible for lysing PDAC cells, blocking mAbs against ICAM-1, DNAM-1, NKG2D, and/or NCR (NKp46, NKp44, NKp30) were added to in vitro51Cr-release assays using MIA PaCa-2 or autologous tumor cells as targets." (PMID 31024520, 2019). "Here we describe a role for DAPK in regulating ICAM1 and subsequently in interaction with ECM components of the tumor microenvironment." (PMID 31772156, 2019). "Butyric acid enhanced granulocytic maturation of AML cells, and just like other HDACi, induced expression of costimulatory and adhesion molecules (CD80, CD86, HLA-DR, HLA-ABC, and ICAM-1) in AML cells, inducing anti-tumor immune responses." (PMID 31739588, 2019). "We show that IL-33 recruits eosinophils indirectly, via stimulation of tumor cell-derived chemokines, while it activates eosinophils directly, up-regulating CD69, the adhesion molecules ICAM-1 and CD11b/CD18, and the degranulation marker CD63." (PMID 31717819, 2019). "In the attempt to identify possible molecules mediating adhesion of eosinophils to tumor cells, we focused on the integrins CD11a/CD18, CD11b/CD18, and ICAM-1." (PMID 31717819, 2019).
tumor (continued). "ICAM‐1 and VCAM‐1 play an important role in promoting adhesion of inflammatory sites, controlling tumour progression and metastasis and regulating immune response." (PMID 30950217, 2019). "Ewing cells were treated with recombinant IFN-γ or vehicle control and tumor cell ICAM1 mRNA and ICAM-1 protein expression was then examined both by RT-PCR and flow cytometry analysis, respectively." (PMID 31164960, 2019). "VEGF-A decreases the adhesive interaction between lymphocytes and tumor vascular endothelial cells, and reduces TIL penetration through deregulation of intercellular adhesion molecule-1 (ICAM-1) and vascular cell adhesion-molecule-1 (VCAM-1)." (PMID 30200478, 2018). "Accordingly, we were able to demonstrate tumor escape using supernatant from the muscle invasive UBC cell line (5637), where the supernatant contained soluble ICAM-1 and TGFβ2 that induced perforin downregulation." (PMID 29966014, 2018). "And by doing these, it increases intercellular adhesion molecule-1 (ICAM-1) and vascular cell adhesion molecule-1 (VCAM-1) in endothelial cells of tumor." (PMID 29849819, 2018). "In comparison with the control group, except for miR-204-5p, the expression levels of ITGA2, FN1, ICAM1, CDH2, TIMP1, CLDN1, TNFRSF12A, miR-146b, and miR-222 were all up-regulated in the tumor group, consistent with the results of the bioinformatics analyses." (PMID 30414611, 2018). "Analysis of genetic profile demonstrated immune‐related DEGs that closely correlated with tumor microenvironment including immune cell recruitment (CCL8) and trafficking (ICAM‐1)." (PMID 29938166, 2018). "Ligands for the endothelial cell adhesion molecules ICAM-1, VCAM-1, E-selectin and N-cadherin were found to be expressed on tumor cells and to mediate tumor-endothelial cell interaction." (PMID 30204757, 2018). "We detected proteins DNMT1, ICAM1 and AIF1 as being highly expressed in the outlier presumed normal tissue compared to both other controls and tumor tissue from the same patients." (PMID 30419021, 2018). "Two additional genes (CD14 and CSNK2A1) were dysregulated in MSS tumours and two genes (CARD11 and VCAM1) were downregulated and six genes were upregulated (LYN, TICAM2, ICAM1, IL1B, CCL4 and PTGS2) in MSI tumours." (PMID 29188362, 2018). "The intercellular adhesion molecule 1 (ICAM-1), the vascular cell adhesion molecule 1 (VCAM-1), E-selectin and galectin-3 have been reported to be involved in the interaction of tumor and endothelial cells." (PMID 29100413, 2017). "The adhesion molecules ICAM-1, VCAM-1, E-selectin and galectin-3 as well as the chemokine system CXCL12/CXCR4 have been reported to be involved in the interaction of tumor and endothelial cells." (PMID 29100413, 2017). "The cytotoxic activity against tumor cells that eosinophils can display in vitro depends on the interaction between LFA-1 and ICAM-1, which is upregulated by interleukin-18." (PMID 29099772, 2017). "The ability of I domain CAR T cells to cross-react with murine ICAM-1 allowed for a simultaneous and rigorous assessment of CAR T cell efficacy against human tumor cells and on-target, off-tumor toxicity against murine ICAM-1 on healthy tissues." (PMID 29085043, 2017). "Our results show upregulation of PD-L1, ICAM-1, MHC-class I, HLA-DR, CD95/FasR, and CD270/HVEM after IFNγ treatment, this upregulation is variable across different tumor types." (PMID 28428785, 2017). "Modeling of the data suggests that the effect of IFNγ on NK cell-mediated tumor lysis is mostly dependent on changes in MHC-class I and ICAM-1 expression." (PMID 28428785, 2017). "We also observed that none of these ligands were downregulated by IFNγ; however, CD274/PD-L1, CD54/ICAM-1, HLA-DR, MHC-class I, CD95/FasR, and CD270/HVEM were upregulated in a variety of tumor types." (PMID 28428785, 2017). "To address the mechanism by which p38MAPK enhances tumor angiogenesis we examined the expression of MMP9 and ICAM1." (PMID 28977919, 2017).
tumor (continued). "Membrane-bound ICAM-1 is overexpressed in CAF and acts as a crucial hub to sustain acto-myosin contractility and matrix remodeling in tumor stroma." (PMID 27901489, 2017). "This is illustrated by the ability of many OV strains of coxsackievirus to bind to intercellular adhesion molecule 1 (ICAM-1), which is a cell adhesion molecule that is over-expressed in many tumours)." (PMID 29157300, 2017). "Our results showed that mollugin suppressed not only the expression of MMP-9 and ICAM-1, but also the expression of VEGF, which are major mediators of tumor cell angiogenesis." (PMID 28933726, 2017). "The relationship between tumor-burden and CAR-mediated toxicity is likely a consequence of ICAM-1 biology." (PMID 29085043, 2017). "In fact, earlier in vitro studies have shown that the stimulation of normal and tumor-derived endothelial cells with angiogenic growth factors (VEGF, bFGF) results in substantially suppressed ICAM-1 expression." (PMID 29250531, 2017). "We report here that cyclin D1 expression increases the expression of ICAM1, and the synthesis of pro-inflammatory chemokines IL8, IP10, and RANTES, all able to alter the tumor microenvironment." (PMID 27286258, 2016). "Expression of adhesion molecules, including ICAM-1, VCAM-1, and endothelial leukocyte adhesion molecule-1 (ELAM-1), on endothelial cells is critical for tumor cell invasion and metastases." (PMID 26823953, 2016). "ICAM-1 plays an important role in cell-cell and cell-ECM interactions, especially tumor invasion and cytotoxicity of lymphocytes." (PMID 26847082, 2016). "We also observed increased expression of HLA class I antigens and ICAM-1, as well as the TAAs CEA and MUC1 on the surface of tumor cells upon exposure to vorinostat." (PMID 26862729, 2016). "The expression of ICAM-1 and VCAM-1 adhesion molecules was up-regulated on tumor endothelial cells only when anti-CD40 mAb treatment was combined with sunitinib." (PMID 27385210, 2016). "Active NFκB upregulates the expression of genes such as VEGF-C, iNOS, MMP-9, ICAM-1 and VCAM-1that regulate tumor angiogenesis and promote tumor metastasis." (PMID 27314329, 2016). "We confirmed tumor-specific overexpression for three genes (CDH11, ICAM1 and CLDN3) using qRT-PCR, and demonstrated protein localization specific to the cell surface of tumor cells by IHC." (PMID 27363029, 2016). "In particular, the interaction between ICAM1 and LFA1 is a crucial step in the generation of tumor-specific cytotoxic T lymphocytes (CTLs)." (PMID 26528477, 2015). "Overall, this data are in good line with several studies indicating enhanced ICAM-1 expression to confer an increased lysis of cancer cells by immune cells comprising NK and LAK cells, monocytes and tumor-infiltrating lymphocytes." (PMID 26513172, 2015). "CD112 (Nectin-2, PVRL2) and CD155 (Necl5, PVR) bind CD226 (DNAM-1), which potentiates in vitro the cytotoxicity of NK cells against a wide range of tumor cells; CD58 (LFA-3) binds CD2 and its co-engagement with ICAM-1 increases NK response." (PMID 26106390, 2015). "We next subcutaneously injected Scr- and ICAM1-shRNA transfected cells into NOD-SCID mice and monitored subsequent tumor growths." (PMID 25879517, 2015). "There are several studies indicating cytokine-induced upregulation of ICAM-1 on cancer cells or cancer cell transfection with the ICAM-1 gene to confer increased cytotoxic tumor cell lysis by immune cells." (PMID 26513172, 2015). "Recent studies have shown a correlation between CCN3 expression and tumor progression in many cancers, and CCN3 has been proposed to increase the migration of PCa cells by influencing ICAM-1 expression." (PMID 24721786, 2014). "We performed Western blot and immunohistochemistry analysis to evaluate the expression of ICAM-1 and E2F1 in the indicated tumor tissues." (PMID 24742333, 2014). "The cytotoxic effect of CIK cells against tumor targets is blocked by antibodies directed against LFA-1 and ICAM-1." (PMID 24742333, 2014).
tumor (continued). "ATP or UTP was able to induce ICAM-1 and VCAM-1 expression at very low doses (100 nM) via P2Y2R activation, which indicates that ATP levels within the tumor microenvironment are sufficient to stimulate P2Y2R in MDA-MB-231 or ECs." (PMID 25156554, 2014). "IL-6 increases ICAM-1 expression through the IL-6R, Syk, JNK, and AP-1 signaling pathways and induces tumor migration." (PMID 24398980, 2014). "curcumin has been shown to suppress the expression of a variety of NF-κB regulated gene products involved in carcinogenesis and tumor growth including cyclin D1, VEGF, COX-2, c-myc, Bcl-2, ICAM-1 and MMP-9." (PMID 25866478, 2014). "ICAM1 is considered a marker of HCC stem cells, and its inhibitors suppress HCC tumor formation and metastasis." (PMID 24614035, 2014). "This increases ICAM-1 expression on the tumour vasculature and tumour-specific CD8+ effector/memory T cell trafficking into the tumour, both of which are recapitulated by intravenously administering IL-6 instead of giving whole body hyperthermia." (PMID 25430985, 2014). "Continuous section slides were made and stained for ICAM-1, VCAM-1 and tumor infiltrating CIK cells respectively." (PMID 23799045, 2013). "WISP-1 increases ICAM-1 expression through αvβ3 integrin, ASK1, JNK/p38, and AP-1 signaling pathways and induces tumor migration." (PMID 24205072, 2013). "majorana significantly reduced the expression of several NFκB downstream target genes (MMP-2, MMP-9, uPAR, ICAM-1 and VEGF) involved in tumor metastasis." (PMID 23874773, 2013). "Here, we showed that the tumor cell invasive genes (e.g., MMP-9 and ICAM-1) were all suppressed by Ssd treatment." (PMID 23573150, 2013). "The targeted delivery of drug-loaded nanovesicles was examined on the TNF-alpha-treated human umbilical vein endothelial cells (HUVECs) or ICAM-1 expressing HT1080 cells in vitro and mouse CT26 tumour or human A549 tumour-bearing mice in vivo." (PMID 26082317, 2013). "The externalization of these cytokines depended on tumor cytotoxic effect and revoked up-regulation of immunological regulators such as MHC, B7 and ICAM-1." (PMID 22971726, 2012). "The expression of ICAM-1, MMP-9 and VEGF, which are involved in tumor cells invasion and metastasis, is known to be regulated by NF-κB." (PMID 22768286, 2012). "The expression of MHC class I molecule, adhesion molecule ICAM-1 (CD54) and co-stimulation molecule LFA-3 (CD58) was significantly decreased in LN tumor samples from advanced stage III." (PMID 23284620, 2012). "DCs were evaluated for antigen uptake, and following maturation with LPS and IFN-gamma, DCs were assessed for expression of CD80, CD40, CD86, ICAM-1 and CCR7, production of IL-12p70 and IP-10, and induction of tumor-specific T-cell responses." (PMID 22194898, 2011). "Induction of ICAM-1, MHC class I and II molecules on tumor cells is also important to eliminate these cells in this immunotherapy." (PMID 24212945, 2011). "Each of the viruses grew quickly to high titers in cancer cells expressing ICAM-1 and intratumoral injection of preformed subcutaneous SK-Mel-28 xenografts in mice with CVA13, CVA15 and CVA18 resulted in significant tumor volume reduction." (PMID 21241513, 2011). "Metronomic gemcitabine also significantly increased apoptosis in cancer-associated fibroblasts and induced greater reductions in the tumour levels of multiple pro-angiogenic factors, including EGF, IL-1α, IL-8, ICAM-1, and VCAM-1." (PMID 20531411, 2010). "Radiation has been shown to upregulate endothelial cell adhesion molecules, such as ICAM-1, VCAM-1 and P-selectin, especially in microvascular or tumor endothelial cells." (PMID 20877628, 2010). "ICAM-1 expression decreases CRC metastasis and suppress cancer progression via promoting tumor cell motility and attachment to the extracellular matrix." (PMID 19822019, 2009).